BDNF (brain derived neurotrophic factor)
Diseases named in the same sentence as BDNF in open-access papers (continued):
Sharing a sentence is not in itself a finding about the gene and the disease.
cognitive decline (continued). "As a target organ of estrogen, decrease in estrogen causes various changes in brain function such as a decrease in choline acetyltransferase and brain-derived neurotrophic factor; thus, postmenopausal women experience cognitive decline and more depressive symptoms than age-matched men." (PMID 34698102, 2021). "Interestingly, the mediating effect of plasma BDNF on platelet activity related cognitive decline was significantly lower in CAD patients than in subjects without CAD." (PMID 34557534, 2021). "BDNF rs56164415 TC heterozygotes had the highest scores on the PANSS cognition subscale, and additionally, veterans with PTSD who were carriers of the T allele had increased PANSS cognition scores or stronger cognitive decline than carriers of the C allele." (PMID 33926045, 2021). "However, genes encoding, dystrobrevin-binding protein 1 (DTNBP1), brain-derived neurotrophic factor (BDNF), catechol-O-methyl transferase (COMT) and apolipoprotein E (APOE), have demonstrated a repeated association with cognitive decline." (PMID 34679354, 2021). "Our findings are thus consistent with the hypothesis that higher serum levels of BDNF at earlier stages of the cognitive decline process might reflect an effective compensatory response to pathophysiologic insults." (PMID 34239422, 2021). "Therefore, we cannot explain why OA + OP administration prevented cognitive decline and depressive behaviors from the perspective of increased BDNF mRNA expression." (PMID 34127683, 2021). "Serum BDNF levels also display heterogeneity with respect to gender, therefore the relationship between circulating BDNF levels, gender, BDNF genotype, and age-related cognitive decline is unclear." (PMID 34408648, 2021). "The benefit of EAHE in reducing cognitive decline may be associated with improved blood biomarkers such as calcium, albumin, Hb, Hcy, SOD, BDNF, APOE4, and α-ACT, as well as reduced structural deterioration in the ARC and PHC regions of patients with mild AD." (PMID 32581767, 2020). "Increased BDNF in the blood slowed AD development and cognitive decline." (PMID 32377164, 2020). "Given that BDNF is essential in mediating synaptic plasticity that serves as the cellular basis of learning and memory functions in adults, BDNF may be involved in the progression of the cognitive decline in AD." (PMID 33014535, 2020). "Our recent study showed that smoking was associated with cognitive decline, but not with BDNF levels in a normal population." (PMID 30659208, 2019). "Higher expression of BDNF slows down cognitive decline in the elderly, especially in the setting of advancing AD neuropathology, indicating that the brain BDNF level could be used as a novel marker for evaluating AD progression." (PMID 31293498, 2019). "LIPUS treatment might alleviate aluminium exposure-induced cognitive decline by acetylation regulation of BDNF expression and reducing oxidative stress in the hippocampus." (PMID 30341248, 2019). "Given that the expression of BDNF could potentially improve cognitive decline in AD, the stimulation of the irisin-BDNF axis in the brain may be a promising issue for AD treatment." (PMID 30388754, 2018). "Additionally, the BDNF treatment has the ability to alleviate the aggregation of Aβ and reduce the cognitive decline of the APP/PS1 Tg mice." (PMID 28377712, 2017). "A number of longitudinal studies did not establish any associations between serum BDNF levels and cognitive decline in healthy older adults." (PMID 29258453, 2017). "The BDNF treatment improved the cognitive decline of the APP/PS1 Tg mice." (PMID 28377712, 2017). "Additionally, the BDNF treatment clearly decreased the deposition of Aβ and reduced the cognitive decline of the APP/PS1 Tg mice." (PMID 28377712, 2017). "In a model of AD, upregulation of BDNF ameliorates the cognitive decline of rats." (PMID 28377712, 2017). "Two SNPs associated with cognitive decline, the COMT val158met SNP and BDNF val66met." (PMID 28520803, 2017).
cognitive decline (continued). "However, the cognitive decline was accompanied with an exacerbated decrease of MMP-9 enzymatic activity and reduction of BDNF mRNA and protein levels in brain, which suggest loss of synaptic plasticity." (PMID 27661129, 2016). "The AAV8 vector was used to deliver the human mature BDNF gene into the brain of P301L mice at 3 months of age, before the occurrence of significant neurofibrillary tangle formation, neuronal degeneration and cognitive decline." (PMID 27701410, 2016). "Furthermore, a decline in BDNF levels in the brain occurs with disease progression and is correlated with cognitive decline." (PMID 26257960, 2015). "Abnormalities in BDNF signaling in the hippocampus could explain the cognitive decline seen in patients with TB." (PMID 26075097, 2015). "Increasing BDNF availability in the brain, by diet, may be a viable strategy to counteract cognitive decline with aging." (PMID 26464952, 2015). "Our results suggest that serum BDNF may have limited utility as a biomarker of prospective cognitive decline." (PMID 24670553, 2014). "Together, these findings have led to the hypothesis that reduced BDNF secretion is one mechanism of age-related cognitive decline." (PMID 19412541, 2009). "Our data suggest that reduced secretion of BDNF in the central nervous system is one mechanism that may contribute to age-related cognitive decline." (PMID 19412541, 2009). "Moreover, an increase in BDNF and engaging in activities that employ cognitive functions (e.g., executive functions) may prevent cognitive decline in older adults." (PMID 41409760, 2025). "The severity of cognitive decline and the presence of comorbidities may influence the role of BDNF." (PMID 40513379, 2025). "Furthermore, a decrease in the expression of synaptic proteins such as synaptophysin and BDNF may contribute to reduced hippocampal synaptic plasticity with age, exacerbating cognitive decline (Bettio, Rajendran, and Gil‐Mohapel 2017)." (PMID 39816485, 2025). "Furthermore, as the duration of T2DM increases, the sustained decrease in BDNF and insulin levels may lead to structural changes in the brain, thereby accelerating cognitive decline in patients." (PMID 40933306, 2025). "A number of studies also suggest a positive correlation between improved cognitive indices and BDNF in cancer patients undergoing chemotherapy, thus supporting our hypothesis that in vivo BDNF enhancement is neuroprotective against cranial RT-induced cognitive decline." (PMID 39696694, 2024). "Recent research suggests that systematic exercise could counteract cognitive decline by improving brain blood flow, boosting neuroplasticity through the brain-derived neurotrophic factor (BDNF), and by triggering the release of neurotrophic factors such as insulin-like growth factor (IGF-1)." (PMID 39407758, 2024). "On the contrary, the clinical data suggest that as BDNF Met66 reduces BDNF availability in the CNS, this reduction in neurotrophic factors may allow faster Aβ + related tau hyperphosphorylation, subsequent neurodegeneration and cognitive decline." (PMID 38454193, 2024). "Furthermore, studies have revealed the interaction between BDNF and feelings of loneliness impacting cognitive decline, particularly manifesting as more pronounced semantic memory deterioration and increased feelings of loneliness among participants with lower BDNF expression levels." (PMID 39876995, 2024). "Indeed, understanding the complex interaction among neuroinflammation, microglial activation, and the modulatory effects of BDNF offers promising avenues for therapeutic interventions aimed at mitigating neurodegenerative processes, cognitive decline, and promoting brain health in older adults." (PMID 39656488, 2024).
cognitive decline (continued). "Higher BDNF concentration in subjects with more severe cognitive decline in the combined group of subjects with AD and MCI might suggest a possible compensatory repair mechanism causing the upregulation of BDNF expression in order to counteract the highest burden of AD pathology." (PMID 36979505, 2023). "Similarly, the present study showed that WHH1889 administration partially reversed the decline in hippocampal BDNF levels, suggesting that BDNF could be a crucial factor in the beneficial effects of WHH1889 on cognitive decline associated with aging." (PMID 37686884, 2023). "This may help explain how the BDNF may be crucial for initiating and maintaining the maladaptive neuroplasticity that underlies persistent pain and its relationship to DPMS dysfunction and cognitive decline." (PMID 36248031, 2022). "However, in order to be able to design strategies to delay the aging associated cognitive impairment in humans, we still need a better understanding of the interplay between factors like NAD+, BDNF, DNA repair and mitochondrial function in relation to aging and cognitive decline." (PMID 35585026, 2022). "The cognitive decline in the aging process is regulated by the increased expression of caspase-1, a protein that regulates the maturation and secretion of interleukin (IL)-1β and IL-18, and decreased expression of BDNF, a protein that improves synaptic connectivity." (PMID 34526890, 2021). "Thus, we hypothesized that a chronic HCD contributes to the cognitive decline in aged rats and that this could be related to altered synaptic plasticity and BDNF signaling." (PMID 34940136, 2021). "In addition, it remains unclear whether administering BDNF after the onset of cognitive decline would be an efficacious treatment." (PMID 32676979, 2021). "In addition to AD hallmarks, we investigated BDNF effects on microglia presence in the brain of AD11 mice, since alterations in microglia activation have been associated with ageing-related cognitive decline and with the progression of neurodegenerative diseases, including AD." (PMID 32676979, 2021). "Supporting this hypothesis, direct administration of BDNF, viral overexpression of BDNF or BDNF secreted from grafted stem cells improve age related cognitive decline and also rescue cognitive decline in a preclinical mouse models developing Aβ and tau pathologies." (PMID 30804738, 2019). "This could suggest that the loss of hippocampal BDNF is not part of the mechanisms involved in age-related cognitive decline." (PMID 31440144, 2019). "It has been hypothesized that this effect could be related to changes in the level of cleavage, since cleavage molecules such as tPA are known to decline with age which could create a paradoxical effect where greater BDNF secretion would, in fact, lead to cognitive decline." (PMID 31440144, 2019). "Considering the combination of these facts, we are confident that our observations are due to true associations of BDNF Val66Met polymorphism with reduced odds of subjective cognitive decline rather than the confounding effects of fatigue or other psychosocial factors." (PMID 30382534, 2019). "Interestingly, deletion of the p66Shc gene in mice leads to an improvement in age-dependent cognitive decline, as well as significant increases in levels of the neurotrophin brain derived neurotrophic factor (BDNF) in the hippocampus and sustained hippocampal neurogenesis." (PMID 30459314, 2018). "Despite the lack of cognitive decline, these results might suggest a selective brain network vulnerability due to the carriage of the BDNF Met allele, which is linked to a potential progression to dementia." (PMID 30333719, 2018). "Butyric acid-producing bacteria, such as Clostridium butyricum, have shown to improve cognitive decline and histopathological changes in the CA1 area of the hippocampus in vascular dementia (VaD) mice, which was associated with a significant increase in BDNF levels and an increase in fecal butyrate." (PMID 30618722, 2018).
cognitive decline (continued). "In this study, we hypothesize that increments in domains of executable functions due to the exercise regulation of BDNF in aging individuals undergoing cognitive decline depend on greater amounts of exercise-dependent BDNF stimuli than do those of memory and cognitive processing." (PMID 28469588, 2017). "Although these studies highlight the potential of targeting BDNF/TrkB signaling, this strategy has not yet been tested in a model that develops the disease features that are most closely associated with cognitive decline in AD: severe synaptic and neuronal loss." (PMID 24614170, 2014). "Further research is required to clarify BDNF dynamics and to determine GDNF's role in motor progression and cognitive decline." (PMID 41697575, 2026). "More broadly, neuropathic pain–induced reductions in hippocampal BDNF limit synaptic efficacy, whereas activation of the cAMP response element-binding protein (CREB)/BDNF pathway protects against pain-related cognitive decline." (PMID 41195280, 2025). "Lower BDNF and higher SAA levels suggest a potential link between systemic inflammation and cognitive decline in IBD, particularly in UC patients." (PMID 40217741, 2025). "Analysis of all dialysis-induced cognitive decline cases revealed that the area under the ROC curve for α-klotho, FGF-23, IL-6, TNF-α, BDNF, BMI, and calcium were 0.58, 0.55, 0.58, 0.59, 0.70, 0.64, and 0.62, respectively." (PMID 40950978, 2025). "Exercise, a key modulator of BDNF levels, activates the PGC-1α/Irisin/BDNF pathway, helping to protect neurons from ROS damage and alleviate cognitive decline." (PMID 40161268, 2025). "Depletion of BDNF and PSD95 contributes to synaptic dysfunction, leading to cognitive decline and memory impairment, as seen in diseases like AD." (PMID 40918527, 2025). "This probiotic can also increase BDNF levels in the CA1 region of the hippocampus, which is crucial for brain health, memory, and combating cognitive decline." (PMID 41601564, 2025). "The experimental groups treated with linagliptin or saxagliptin showed a reduction in the degradation of both HIF1α and BDNF, NT4, leading to decreased cognitive decline compared to the diabetic mice." (PMID 38860903, 2025). "PA, particularly aerobic exercise programs, have a direct impact on brain plasticity and neurogenesis by promoting the production of neurotrophic factors like brain-derived neurotrophic factor (BDNF), which helps prevent cognitive decline." (PMID 39584899, 2024). "Combined with sustained elevation of BDNF and promotion of neural plasticity, MPA can protect against and delay cognitive decline through long-term regulatory effects." (PMID 39459642, 2024). "Alleviate age-related cognitive decline in learning and memory in accelerated ageing mouse (SAM) models, upregulate increased expression of neurotrophic factors such as BDNF and NT-3 at the mRNA and protein levels." (PMID 39867560, 2024). "In alcohol-induced neurodegeneration and cognitive decline, the reduction in extracellular signal regulatory kinase (ERK1/2) and c-AMP-response element-binding protein (CREB) largely inhibits brain-derived neurotrophic factor (BDNF)." (PMID 39126094, 2024). "Galangin can mitigate the doxorubicin-provoked suppression of hippocampal BDNF while upregulating GFAB, thus preventing cognitive decline in rats." (PMID 39770491, 2024). "In our study, BDNF levels were reduced in the plasma of HIV-infected individuals on ART following lithium treatment, indicating a possible cognitive decline in the future in these individuals." (PMID 36790601, 2023). "Reduction in BDNF, SYN, and PSD95 has been reported in the hippocampus of patients with AD or cognitive decline." (PMID 36810115, 2023). "We determined that the level of hippocampal BDNF was significantly decreased in the CORT-treated control group, which was correlated with cognitive decline in the passive avoidance test (PAT), following CORT injection in mice." (PMID 35684372, 2022).
cognitive decline (continued). "It is well known that brain-derived neurotrophic factor (BDNF) is a neurotrophin that plays a key role in brain physiology and cognitive decline." (PMID 36670866, 2022). "Considering a decrease in BDNF concentration is a cardinal feature of cognitive decline and the known effect of BHB to stimulate BDNF expression, relatively little research has been done exploring how ketogenic interventions influence plasma BDNF in humans." (PMID 36138878, 2022). "Thus, BDNF could be considered as o protective factor against cognitive decline." (PMID 36498709, 2022). "AD-derived cognitive decline is closely related to alterations of neurotrophic factor levels, such as nerve growth factor (NGF) and brain-derived neurotrophic factor (BDNF), and changes in blood flow." (PMID 34138944, 2021). "In summary, our findings indicate that NF-α1-CPE is a more critical trophic factor than BDNF for the prevention of CA3 neuronal cell death and cognitive decline with severe stress in mice." (PMID 33414376, 2021). "This brief article focuses on how the downregulation of ZPR1 by a high-fat diet can contribute to cognitive decline by directly influencing the concentration of PPAR-γ and indirectly reducing the concentration of BDNF to decrease neural plasticity." (PMID 34746842, 2021). "Several studies showed that the cognitive decline triggered by these environmental contingencies could be attributed to a hippocampal oxidative imbalance or a decrease in synaptic plasticity via the reduction of brain-derived neurotrophic factor (BDNF) levels after sleep deprivation or US." (PMID 31428001, 2019). "Long-term DL-NBP treatment reduced the cognitive decline in SAMP8 mice by regulating structural synaptic plasticity, likely via enhancement of BDNF/TrkB signaling." (PMID 30026693, 2018). "It is plausibly assumed that executive processes may require larger amounts of exercise-dependent BDNF support than what is commonly achieved through acute experiments at memory and cognitive processes, especially for individuals under pathological processes of cognitive decline." (PMID 28469588, 2017). "However, the exact mechanisms by which moderate amounts of BDNF affect cognitive function require further study; such knowledge might serve as a reference for the development of novel strategies to attenuate cognitive decline and inhibit neurodegeneration in BD." (PMID 27905499, 2016). "The lack of neurotrophic factors, such as BDNF, further compromises neuronal survival and plasticity, contributing to cognitive decline." (PMID 40806031, 2025). "The study also found that in the co-culture, BDNF and NGF levels increased after treatment with the test substances, suggesting the potential of the formulation in promoting neurogenesis and its utility in cognitive decline." (PMID 40807615, 2025). "Physical exercise, as a non-pharmacological intervention, has been shown to delay cognitive decline by enhancing BDNF expression, reducing neuroinflammation, and regulating hormonal balance." (PMID 40867144, 2025). "Longitudinal studies are needed to determine whether changes in BDNF and CRP levels over time are predictive of cognitive decline in bipolar disorder, as this would clarify temporal relationships and strengthen causal inference." (PMID 41367212, 2025). "Experimental and translational work indicates that enriched environments increase the expression of neurotrophic factors such as brain-derived neurotrophic factor (BDNF), promote hippocampal neurogenesis and synaptic plasticity, and exert neuroprotective effects against cognitive decline." (PMID 41375914, 2025). "Furthermore, it impairs synaptic plasticity by reducing brain-derived neurotrophic factor (BDNF) levels, disrupting long-term potentiation (LTP), and accelerating cognitive decline." (PMID 40458441, 2025).